SNORD116-30 (small nucleolar RNA, C/D box 116-30)
Synonyms: HBII-85-30
Gene: Small nucleolar RNA gene on chromosome 15 (25,108,268 to 25,108,352, forward strand). Ensembl gene ENSG00000252277.
Gene Ontology:
Biological process: RNA processing
Cellular component: nucleolus
Homologues: Orthologues: mouse Gm22373 (52% identical), rat LOC120100337 (47% identical). Paralogues in human: SNORD116-26 (86% identical), SNORD116-25 (84% identical), SNORD116-27 (81% identical), SNORD116-29 (80% identical), SNORD116-28 (79% identical), SNORD116-2 (72% identical), SNORD116-20 (72% identical), SNORD116-6 (72% identical), SNORD116-14 (71% identical), SNORD116-16 (71% identical), SNORD116-17 (71% identical), SNORD116-19 (71% identical), and 20 more.